IRS1 (insulin receptor substrate 1)
Diseases named in the same sentence as IRS1 in open-access papers (continued):
Sharing a sentence is not in itself a finding about the gene and the disease.
Insulin resistance (continued). "Yerba maté significantly improved insulin resistance by restoring hepatic and muscle IRS-1 and AKT phosphorylation and by controlling adipose tissue inflammation associated with obesity." (PMID 25621503, 2015). "We examined the changes in the phosphorylation of insulin receptor substrate-1 (IRS-1) in PA-treated HepG2 cells to assess insulin resistance." (PMID 26077338, 2015). "For instance, it has been shown to reduce hyperglycemia and attenuate insulin resistance in part, by inhibiting the ubiquitin-proteasome pathways mediating degradation of insulin receptor substrate 1 and 2, critical mediators of insulin signaling." (PMID 26045713, 2015). "The phosphorylation of serine residues in IRS1 was previously reported to be increased in models of insulin resistance and type-2 diabetes." (PMID 26084330, 2015). "It has been reported that luteolin ameliorated inflammation related endothelial insulin resistance in an IKKb/IRS-1/Akt/eNOS-dependent pathway." (PMID 26705405, 2015). "Obesity and inflammatory cytokines secreted from adipose tissues induce IRS-1/2 degradation in insulin target tissues, which is thought to be one of the mechanisms for the onset of insulin resistance and type 2 diabetes." (PMID 26074875, 2015). "Elevated FFA secretion associated with fat mass expansion is widely believed to play an important part in insulin resistance with it affecting the phosphorylation of IRS-1 and pathways that link into this." (PMID 25876175, 2015). "MiR-126 expressed in human hepatocytes is involved in the development of insulin resistance through the inhibition of insulin receptor substrate 1 (IRS1)." (PMID 25710020, 2015). "Protein tyrosine phosphatase 1B (PTP1B), which can directly dephosphorylate both the insulin receptor and insulin receptor substrate 1 (IRS-1), thereby terminating insulin signaling, reportedly plays an important role in insulin resistance." (PMID 26402673, 2015). "Structural modification by hyperphosphorylation of serine at residues Ser302, Ser307, Ser612, and Ser632 in IRS1 was suggested to be an important mechanistic element responsible for increased insulin resistance in rodent models." (PMID 26693205, 2015). "IRS-1 is a highly polymorphic gene, located at 2q36, and its Gly972Arg variant is usually found in DM2 patients, especially in those who have insulin resistance, suggesting an important role of this polymorphism in the pathogenesis of diabetes." (PMID 25859280, 2015). "Although mechanisms involved in TNFα-induced insulin resistance are not completely understood, compelling evidence indicates that TNFα inhibits IRS-1- and IRS-2-mediated PI3-kinase activation, leading to insulin resistance." (PMID 26077338, 2015). "Overactivated S6K1 via phosphorylation of insulin receptor substrate-1 (IRS-1) is a pivotal mechanism that induces insulin resistance." (PMID 25592553, 2015). "Previous studies have shown that PTP1B overexpression inhibits phosphorylation of IR and IRS-1, leading to insulin resistance." (PMID 26193288, 2015). "Homozygous interruption of IRS1 expression in mice led to mild insulin resistance, while complete depletion of IRS2 expression in rodents resulted in severe insulin resistance." (PMID 26693205, 2015). "The secreted IL-1β binds to IL-1R and activates NF-κB and MAPK pathways, thereby impairing insulin signaling through the activation of IRS-1 in adipocytes leading to insulin resistance." (PMID 26779183, 2015). "TNF-α promotes insulin resistance by inhibiting the IRS1 (insulin receptor substrate 1) signaling pathway." (PMID 26307961, 2015). "Thirdly, it has been reported that globular domain of CTRP5 ameliorates apoptosis and insulin resistance in palmitate-treated myocytes via inhibiting caspase-3 activity, reactive oxygen species accumulation and insulin receptor substrate-1 (IRS-1) reduction." (PMID 26613006, 2015).
Insulin resistance (continued). "TNF-α is a signature proinflammatory cytokine that promotes the expression of other inflammatory cyto-/chemokines and induces insulin resistance by inhibiting IRS-1 signaling pathway." (PMID 26200663, 2015). "The possible link between HCV infection, insulin resistance, and the early phase of viral kinetics during antiviral treatment involves the downregulation of IRS1/2 and upregulation of the suppressor of cytokine signaling-3 (SOCS-3) genes in liver tissue." (PMID 25821463, 2015). "Recently, we observed a higher frequency of the IRS-1 972Arg polymorphism in DM2 and GDM pregnant women, and also a direct link between this gene variant and obesity and insulin resistance." (PMID 25859280, 2015). "We next explored inhibitory serine phosphorylation of IRS1 as the source of insulin resistance downstream of IR in the white adipose tissue." (PMID 26512886, 2015). "Transgenic mice with muscle-specific IRS-1 serine to alanine are protected from fat-induced insulin resistance in skeletal muscle." (PMID 25309812, 2014). "This target is considered to be critical since the levels of PTP1 expression are consistent with the degree of inhibition of IRS1 tyrosine phosphorylation and GLUT4 translocation that are associated with insulin resistance in the clinical setting." (PMID 25120613, 2014). "Increased IRS-1 phosphorylation of serine and threonine residues, in particular Ser307, contributes to the defective IRS-1 tyrosine phosphorylation in insulin-resistance." (PMID 25120613, 2014). "A high level of plasma RBP4 can enhance insulin resistance through inhibition of IRS-1 and activation of phosphatidylinositol 3-kinase (PI3-K) in skeletal muscles." (PMID 24604418, 2014). "The peroxisome proliferator-activated receptor gamma (PPARG), Pro12Ala and the insulin receptor substrate (IRS1), Gly972Arg confer opposite effects on insulin resistance and type 2 diabetes mellitus (T2DM)." (PMID 24447396, 2014). "TNFα is known to induce insulin resistance in rodents and decrease the expression of insulin receptor, IRS-1, and GLUT4 in 3T3-L1 adipocytes." (PMID 24918199, 2014). "The effect of pro-inflammatory cytokines that induces insulin resistance begins by the ameliorated tyrosine phosphorylation of insulin receptor substrate (IRS)-1." (PMID 25239110, 2014). "Insulin resistance can arise from defects in insulin signaling events (typically at the levels of IRS-1 or Akt)." (PMID 24705014, 2014). "Under the condition of ER stress, activated c-Jun N-terminal kinase (JNK) inhibits insulin signaling through phosphorylation of IRS-1 at serine 307, leading to the development of insulin resistance." (PMID 24474199, 2014). "In particular, IL-6 seems to induce insulin resistance impairing hepatic signalling and affecting the phosphorylation of insulin receptor substrate 1 (IRS-1), glucose transporter 4 (GLUT–4), and other specific transcription factors." (PMID 25548896, 2014). "Increased phosphorylation of IRS-1 would be expected to directly inhibit binding of the insulin receptor to IRS-1 and thus block normal insulin stimulation of its receptor, causing insulin resistance." (PMID 25352752, 2014). "It is therefore likely that the reduction in IRS-1 in the offspring of obese dams observed here contributes to their development of insulin resistance." (PMID 24749062, 2014). "The two most important substrates of P-JNK, c-Jun and IRS-1 play important roles in the induction of apoptosis and insulin resistance." (PMID 24896641, 2014). "ER stress dependent activation of JNK is one of the main pro-apoptotic events, which also favors insulin resistance by means of Ser-phosphorylation of IRS-1." (PMID 24896641, 2014). "IRS-1 is involved in insulin resistance and is involved in the regulation of glucose uptake and conversion into fat cells." (PMID 24312255, 2013).
Insulin resistance (continued). "Insulin resistance is associated with the activation of JNK and subsequent JNK-mediated serine phosphorylation of IRS-1 at Ser-307 that negatively regulates the insulin signaling pathway." (PMID 23829668, 2013). "Activated JNK can promote insulin resistance through serine phosphorylation of insulin receptor substrate 1 (IRS-1) and also via the induction of proinflammatory cytokines that feed back and further activate JNK." (PMID 24167585, 2013). "Such a role of phosphorylation of IRS1 at Ser307 makes the Ser307-kinase a potential target for treatment of insulin resistance." (PMID 23565163, 2013). "We found increased levels of the phosphorylated form of the insulin resistance marker IRS-1 ser 307 and decreased levels of the downstream target AKT in T2DM rat hippocampus." (PMID 23829668, 2013). "States indicative of Type II diabetes were indicated by insulin resistance induced by TNFα, through the inhibition of tyrosine (tyr) phosphorylation of IRS1." (PMID 24324517, 2013). "IL-6-mediated insulin resistance involves activation of proinflammatory kinases that converge at the IRS-1 level." (PMID 23533500, 2013). "RBP4 inhibits insulin-induced phosphorylation of IRS1 suggesting that adipocyte secreting RBP4 induces insulin resistance." (PMID 23781214, 2013). "In our study, IRS1 was downregulated in the omental adipose tissue, suggesting increased insulin resistance in that tissue." (PMID 26029481, 2013). "The heart is thought to be a resistin target where it enhances phosphorylation of insulin receptor substrate-1 and thus insulin resistance, impacting glucose transport." (PMID 24205240, 2013). "In particular, the mRNA down-regulation of Insr, Irs1 and Irs2, in association with reduced phosphorylation of Akt and reduced Glut4 expression, suggests that Zip7 activity may be amenable to manipulation as a novel approach for the treatment of insulin resistance in skeletal muscle." (PMID 24265765, 2013). "TNF-α also induces serine phosphorylation of IRS1 to modulate the downstream effectors of the insulin receptor resulting in insulin resistance." (PMID 23781214, 2013). "S6K-mediated phosphorylation of IRS1 at Ser636/Ser639 is inhibitory for insulin signaling resulting in insulin resistance." (PMID 28548055, 2013). "Other reports also pointed out that the blockage of p38 MAPK accomplishes its anti-insulin resistance effect by decreasing both phosphorylation and basal expression of IRS1/2 genes." (PMID 22278044, 2013). "Saturated fatty acids such as palmitate elevated sphingolipid concentrations and subsequently induced insulin resistance via the inhibition of PKB or IRS1 phosphorylation." (PMID 24376889, 2013). "Due to increased PTEN activation, the AKT pathway, which includes S6K, would be reduced, leading to less phosphorylation by S6K of IRS1 and thus, less insulin resistance." (PMID 28548055, 2013). "In our model, the decline in IRS-1 mRNA was proposed to account for GC-induced insulin resistance in skeletal muscle, and the time course changes of IRS1m/IRS1m0 was used to modify the sensitivity factor SIG." (PMID 24312573, 2013). "Many of the T2D susceptibility genes identified by GWAS affect β cell function (cell cycle regulation), and only a limited number of T2D GWAS loci are associated with insulin resistance (e.g., PPARG, FTO, IRS1 and KLF14)." (PMID 23997649, 2013). "Sreejayan also showed that markers of insulin resistance (phospho-c-Jun and IRS-1 phosphoserine) and ERS (p-PERK, p-IRE-1A, p-eIF2α) were elevated in liver and cultured muscle cells in ob/ob mice." (PMID 23829668, 2013). "And serine phosphorylation of insulin receptor substrate-1 (IRS-1) is a key event linking inflammation and insulin resistance." (PMID 23840461, 2013). "Our data suggest that there are relatively few cases of defective IRS1-PKB signalling that correlate with obesity induced insulin resistance in an otherwise healthy population." (PMID 23468892, 2013).
Insulin resistance (continued). "ERK1 is an important mediator of inflammation-induced insulin resistance, insulin receptor substrate (IRS)-1 serine (inhibitory) phosphorylation, and the inhibitory effect of TNFα on insulin signaling." (PMID 23431246, 2013). "IRS-1 is a key protein upstream of PI3 K and Akt, and inhibition of its expression or tyrosine phosphorylation is often associated with insulin resistance." (PMID 23983791, 2013). "In contrast, inhibition of Rho/ROCK signaling reduces insulin resistance by increasing the tyrosine phosphorylation of IRS1/2 and Akt phosphorylation." (PMID 23776620, 2013). "Pro-inflammatory cytokines, particularly tumor necrosis factor-α (TNF-α), can enhance the serine phosphorylation of insulin receptor substrate-1, a crucial event in the induction of insulin resistance." (PMID 22880019, 2012). "TNF induces phosphorylation of IRS-1 at serine instead of tyrosine residues and promotes insulin resistance." (PMID 22691241, 2012). "Individual SNPs for which we found an association with MetS were MC4R rs17782312 which is involved in weight regulation and IRS1 rs2943634 which is involved in insulin resistance." (PMID 23101478, 2012). "Lipid-induced insulin resistance is typically associated with increased phosphorylation of atypical PKC isoforms and inhibitory (serine) phosphorylation of IRS1." (PMID 22973301, 2012). "Accordingly an IRS1 knock-out mouse model displayed a MetS like phenotype with insulin resistance, increased blood pressure, increased triglycerides, decreased HDL cholesterol and decreased LPL activity." (PMID 23101478, 2012). "In experiments with high fat fed obese rats, activity of the mTOR pathway is elevated in skeletal muscle and leads to inhibitory phosphorylation of IRS1, impaired Akt signaling, and insulin resistance." (PMID 22545721, 2012). "JNK and IKK are the key stress-activated kinases to disrupt insulin signal transduction by serine-phosphorylating IRS1/2 leading to insulin resistance in HFat-fed mice." (PMID 22355328, 2012). "In fact, high leptin levels affect insulin binding to its receptor and reduce IRS-1/2 intracellular mediators downstream, thereby potentiating and perpetuating overall insulin resistance." (PMID 23091482, 2012). "This leads to serine/threonine phosphorylation of insulin receptor substrate-1 and -2, and eventually to insulin resistance." (PMID 22765047, 2012). "Activation of JNK, in particular the JNK1 isoform, phosphorylates IRS-1 at sites that prevent its recruitment to the activated insulin receptor thus preventing propagation of insulin signaling and promoting insulin resistance." (PMID 24764512, 2012). "Our western blot assays demonstrated significant reduction in p-Ser312 IRS-1 and increase in p-AKT levels, associated with reduction in HOMA-IR in patients with active RA and high baseline insulin resistance." (PMID 22691241, 2012). "Western blot analysis in seven active RA patients with high insulin resistance showed reduction in p-Ser312 IRS-1 (P = 0.043) and increase in p-AKT (P = 0.001) over the study period." (PMID 22691241, 2012). "It is thought that JNK-mediated phosphorylation of serine residues in IRS1 inhibits the phosphorylation of IRS1 on tyrosine residues and leads to insulin resistance." (PMID 22934019, 2012). "TNFα and IL-6 have been shown to inhibit insulin signaling through inhibitory phosphorylation of IRS1; ablation of these cytokines prevents insulin resistance in cells and in vivo." (PMID 24764512, 2012). "Strong evidence suggests that muscle accumulation of diacylglycerol and long chain acyl-CoA leads to insulin resistance through the activation of serine protein kinase C, which impairs insulin receptor and IRS-1 tyrosine phosphorylation." (PMID 22359625, 2012). "TNF-α contributes insulin resistance by blunting the insulin-stimulated tyrosine phosphorylation of IRS-1, inhibiting glucose uptake, and activating NFκB pathway." (PMID 22778500, 2012).
Insulin resistance (continued). "Experimentally, upregulation of SOCS-1 and -3 in the liver leads to insulin resistance through several mechanisms, including degradation of IRS1 and IRS2 inhibition of insulin receptor kinase activity, and downregulation of IFN-associated innate immunity." (PMID 22701799, 2012). "Our studies here show that p/CIP and αSRC-1 control IRS1 levels and determine insulin resistance in age-related and high fat diet-induced obesity models." (PMID 22859932, 2012). "Depending upon the genotype, HCV induced Insulin resistance can be promoted by a number of mechanisms like Genotype 1 can deteriorate IRS-1 by the ubiquitinylation favored by SOCS-3." (PMID 22008087, 2011). "IRS-1 is decreased in skeletal muscle and liver of animal models established for insulin resistance and type 2 diabetes, such as ob/ob mice and Zucker fatty rats." (PMID 21464990, 2011). "Mitochondrial dysfunction resulting from genetic (mitochondrial DNA depletion) or metabolic inhibition (Rotenone or Antimycin A) induced insulin resistance in hepatocytes via a reduction in the expression of IRS-1 protein." (PMID 21464990, 2011). "Mitochondrial dysfunction induces insulin resistance in myocytes via a reduction of insulin receptor substrate-1 (IRS-1) expression." (PMID 21464990, 2011). "Our findings in hepatocytes reveal a novel mechanism for the development of insulin resistance by providing the first direct evidence that miR-126 mediates the repression of IRS-1 expression in mitochondrial dysfunction." (PMID 21464990, 2011). "In the present study, we demonstrated that mitochondrial dysfunction resulting from genetic or metabolic inhibition induced the development of insulin resistance in hepatocytes via a reduction of IRS-1 expression." (PMID 21464990, 2011). "In genotype 3, there is enhanced production of SOCS7 that diminishes IRS-1 and promotes insulin resistance." (PMID 22008087, 2011). "Gene variants related to insulin resistance such as insulin gene (VNTR), insulin receptor (INSR), insulin receptor substrate proteins (IRS1/2) and calpain-10 have shown to be associated with PCOS and related metabolic abnormality." (PMID 21492415, 2011). "There have been several reports demonstrating that persistent stimulation of aldosterone induces IRS-1 degradation, thus leading to insulin resistance." (PMID 21933140, 2011). "Several lines of evidence suggest that a reduction in IRS-1 protein plays an important role in the development of insulin resistance and type 2 diabetes." (PMID 21464990, 2011). "In the present study, we demonstrated that mitochondrial dysfunction resulting from genetic or metabolic inhibition provoked insulin resistance via a decrease in the expression of IRS-1." (PMID 21464990, 2011). "The main cellular molecular mechanism of insulin desensitization, with consequent insulin resistance presents in MetS-patients, involves increased serine phosphorylation and decreased tyrosine phosphorylation of IRS-1." (PMID 20809949, 2010). "Inflammatory cytokines like TNFα, can act as mediators of insulin resistance by impairing the tyrosine kinase activity of both the insulin receptor (IR) and insulin receptor substrate (IRS-1), thus inhibiting insulin signaling." (PMID 20634940, 2010). "In vitro studies have shown that chemerin induces insulin resistance at the levels of IRS1, Akt, and GSK3 phosphorylation and glucose uptake." (PMID 22375203, 2010). "This resulted in the insulin resistance marked by the down-regulation of insulin receptor signalling (Irs1, Foxo1, and Foxo3a), and down-regulation of Glut4." (PMID 19344534, 2009). "It is GRK2 which mediates endothelin-1-induced insulin resistance via the inhibition of both Gαq/11 and insulin receptor substrate-1 pathways in these cells." (PMID 20204079, 2009).